TFRC (transferrin receptor)
Diseases named in the same sentence as TFRC in open-access papers (continued):
Sharing a sentence is not in itself a finding about the gene and the disease.
cervical carcinoma (continued). "We also found that TFRC expression was significantly elevated in cervical cancer (CESC) according to both TCGA and GSE9750 datasets." (PMID 40303995, 2025). "Analysis of clinical data demonstrated a notable correlation between TFRC expression levels and the T stage of cervical cancer patients." (PMID 39131609, 2024). "Immunohistochemistry and qPCR was employed to assess TFRC mRNA and protein expression in 33 cases of cervical cancer." (PMID 39131609, 2024). "Six interesting core DEPs (SPARC, HPX, VCAM1, TFRC, ERN1 and APMAP) were confirmed to be potential plasma diagnostic markers for LVSI and LNM in cervical cancer patients." (PMID 37689639, 2023). "TFRC was reported to be related to the prognosis of cervical cancer patients by participating in the JAK-STAT pathway and HIF-1 signalling pathway in some bioinformatics analysis articles." (PMID 37689639, 2023). "We found that among the molecules demonstrating correlation, excluding IRF-1 and TFRC, expression in cervical cancer was negatively correlated with hsa_circ_0000276 expression, and expression of the key genes was positively correlated with one another." (PMID 36894874, 2023). "But, expression of transferrin receptor 1 (TfR1), a poor prognostic indicator in cervical cancer, was increased." (PMID 36700235, 2022). "Desferal (deferoxamine) controls the expression of human copper transporter 1 and transferrin receptor 1 via Sp1, and it exhibited synergistic cytotoxicity in combination with oxaliplatin in human cervical cancer cells." (PMID 35550011, 2022). "SCD and TFRC were expressed in both normal cervical and cervical cancer tissues, while CA9 was expressed in only cervical cancer tissues." (PMID 36313765, 2022). "A previous research group established a 4-gene signature related to ferroptosis of cervical cancer patients (TFRC, ACACA, SQLE and PHKG2)." (PMID 36313765, 2022). "Finally, we confirmed that immunosuppression in cervical cancer is closely related to high TFRC expression." (PMID 40303995, 2025). "We confirmed that immunosuppression in cervical cancer was closely related to high TFRC expression." (PMID 40303995, 2025). "Notably, the ubiquitination pathway, acting as a crucial regulatory hub, may modulate TFRC-involved iron homeostasis balance and associated cancer pathways through mechanisms such as targeted protein degradation, consequently influencing the cellular biological behaviors of cervical cancer." (PMID 40809844, 2025). "Notably, TFRC expression in cervical cancer tissues was significantly greater than in high-grade squamous intraepithelial lesions (HSIL)." (PMID 40303995, 2025). "Together, the results suggested that CA9, TFRC, and SCD were risk factors for cervical cancer." (PMID 36313765, 2022). "CA9, TFRC and SCD are all risk factors for cervical cancer, so we predicted candidate drugs for these genes, among which 2-(4-morpholinyl)-8-phenyl-4H-1-benzopyran-4-one and oxygen could regulate all three of these risk factors." (PMID 36313765, 2022). "TFRC expression is up-regulated in cervical cancer compared with normal cervix." (PMID 33671013, 2021). "But HPV-mediated immune alteration analysis using The Cancer Genome Atlas shows that upregulation of TFRC may relate to a poor prognosis of survival of cervical cancer patients." (PMID 32849815, 2020). "Also, IPA diseases analysis data showed 8 proteins were associated with cervical cancer, including ANX1, ANX2, ANX 5, ENO1, HSP90AB1, YWHAE, TFRC, HSP90, and KRT19." (PMID 23243437, 2012). "However, the exact role of TFRC in the development and progression of cervical cancer remains unclear." (PMID 40303995, 2025). "Transferrin receptor 1 (TFRC), a pivotal regulator of iron metabolism, plays a significant role in the initiation and development of cervical cancer." (PMID 40809844, 2025).
cervical carcinoma (continued). "We combined the expression of TFRC and immune cell infiltration to analyze the effect on tumor OS in GEPIA2 that those cell infiltration has an impact on the prognosis in cervical cancer." (PMID 40303995, 2025). "Then, HIF1α binds to the hypoxia response element (HRE) in the nucleus and activates the transcription and translation of transferrin receptor 1 (TfR1) and divalent metal transporter 1 (DMT1), which induces ferroptosis resistance in cervical cancer cells." (PMID 37692513, 2023). "Here we found that it also had the potential to treat cervical cancer, in a mechanism involving CA9, TFRC, and SCD." (PMID 36313765, 2022). "Among the potential targeting genes, SOST, MTA1, TFRC, and YAP1 are involved in some important signaling pathways modulating cervical cancer cell invasion, migration, and drug sensitivity." (PMID 30344797, 2018). "These genes were uploaded to the GEPIA database, which showed that in cervical cancer and paracancerous tissues, the expression levels of seven genes, CD47, FKBP4, IRF-1, LDHA, PDIA3, TFRC, and SLC16A1, were significantly higher in cancer tissues (p < 0.05) than in healthy tissues." (PMID 36894874, 2023). "The ability of SM to inversely down-regulate EFNA1 and TFRC and up-regulate HIST1H2BK and ISG20 could illustrate a probable importance of these genes in SM-induced inhibition of growth of cervical carcinoma cells." (PMID 31523389, 2019).
Alzheimer disease (33 papers, 2016 to 2025). A progressive, neurodegenerative disease characterized by loss of function and death of nerve cells in several areas of the brain leading to loss of cognitive function such as memory and language. "Bispecific antibodies utilizing the transferrin receptor (TfR) for transport into the brain are being developed for both therapeutic and diagnostic targeting of the amyloid-β (Aβ) protein that deposits in the Alzheimer's disease (AD) brain." (PMID 40810143, 2025). "Wang and co-workers observed that treatment with myricetin reduced iron content and inhibited transferrin receptor 1 (TfR1) in human neuroblastoma cells, and significantly reversed scopolamine-induced cognitive deficits in a mouse model of Alzheimer’s disease." (PMID 39063122, 2024). "Myricetin also reduces iron uptake in Caco-2 cells and the iron content in vivo by inhibiting the expression of transferrin receptor 1 (TFR1) in an Alzheimer’s disease mouse model." (PMID 36978878, 2023). "Additionally, TF and TFRC levels show positive correlations with iron content in AD brains, suggesting their potential role in iron dysregulation in Alzheimer’s disease." (PMID 39669708, 2024). "Transferrin receptor 1 (TfR1) mediated brain delivery of antibodies could become important for increasing the efficacy of emerging immunotherapies in Alzheimer's disease (AD)." (PMID 37170266, 2023). "Bispecific antibodies, with one domain targeting the transferrin receptor at high affinity and the other domain directed towards a putative therapeutic target relevant for treating Alzheimer’s disease, i.e., beta-secretase 1, lead to reduction of amyloidogenic peptide formation in the brain." (PMID 36297671, 2022). "For instance, antibodies designed to bind high-affinity receptors, such as those on transport mechanisms like the transferrin receptor or therapeutic targets such as amyloid-beta in Alzheimer’s disease, may experience enhanced retention due to these interactions." (PMID 39767824, 2024). "Instead, it may be advantageous that the BEC expression of the transferrin receptor remains unchanged in Alzheimer’s disease, which further justifies attempts to target transferrin receptors expressed by BECs in the neurodegenerative brain expected to have a near intact BBB." (PMID 36297671, 2022). "Decreased Fpn expression and abnormal iron deposition significantly increased NOX4, 4-HNE, and MDA levels in damaged astrocytes of cerebral cortex, and five hub genes (JUN, SLC2A1, TFRC, ALB, and NFE2L2) closely related to ferroptosis were identified in Alzheimer's disease (AD) patients." (PMID 36062196, 2022). "While Silberberg and colleagues found TFRC and RPLP0 as the most stable reference genes in schizophrenia and bipolar disorders, Penna and colleagues found CYC1 and EIF4A2 as the best reference genes in Alzheimer’s disease." (PMID 27754318, 2016). "In addition, there was a significant positive correlation of the transferrin receptor with iron levels in patients with Alzheimer’s disease, but not in cognitively normal individuals, possibly indicating a response to sequestered iron in the former group." (PMID 38667304, 2024).
COVID-19 (33 papers, 2020 to 2026). A disease caused by infection with severe acute respiratory syndrome coronavirus 2. "Immunostaining and lipidomic analysis in COVID-19 lung autopsies reveal increases in ferroptosis markers, including transferrin receptor 1 and malondialdehyde accumulation in fatal cases." (PMID 38769293, 2024). "Based on relevant results reported in the existing literature and a previous study of our group, the genes CCL5, OAS1, IRF9, IFI6, TGFB1, IL1B, and TFRC were analyzed in the present study in relation to the severity of COVID-19." (PMID 38731851, 2024). "In the present study, the differential expression of seven genes related to immunity, IRF9, CCL5, IFI6, TGFB1, IL1B, OAS1, and TFRC, was analyzed in individuals with COVID-19 diagnoses of different disease severities." (PMID 38731851, 2024). "Currently, no ACE2 inhibitors have been beneficial to COVID-19 patients, and this highlights TFRC as a promising anti-COVID-19 target." (PMID 35860023, 2022). "To evaluate the iron demand of various immune-cell subsets during an active viral infection, we analyzed the differential correlation between the expression of cell-surface markers and that of the transferrin receptor CD71 in patients with COVID-19 compared with HCs." (PMID 38429458, 2024). "TFRC might have an indirect relationship with ACE2 which could explain its overexpression in COVID-19 cases." (PMID 37389217, 2023). "In this study, the relative expression of IRF9, CCL5, IFI6, TGFB1, IL1B, OAS1, and TFRC genes (related to immunity and antiviral activity) was analyzed in upper airway samples from 127 individuals (97 COVID-19 positive and 30 controls) by using a two-step RT-PCR." (PMID 37389217, 2023). "Reported iron-related alterations in the sera of COVID-19 include decrements in iron, transferrin, transferrin saturation and hemoglobin (can show normal levels), and increments in ferritin, hepcidin (can be low), soluble transferrin receptor (in ICU patients) and lipocalin-2." (PMID 35849261, 2023). "Of the five proteins differentially expressed in cMs, four [transferrin receptor (TFRC), sialic acid binding Ig-like lectin 1 (SIGLEC1), Fc fragment of IgG receptor 1a (FCGR1A), and leukocyte-associated Ig-like receptor 1 (LAIR1)] were higher expressed in COVID-19+ cases." (PMID 34429372, 2021). "Free iron was higher than the controls in all patients, with higher levels of hepcidin and soluble transferrin receptor in ARDS and COVID-19." (PMID 34573092, 2021). "Single-cell and bulk transcriptomic profiling of severe COVID-19 lungs further reveal upregulation of iron-regulatory transcripts (FTL, FTH1, TFRC) in pulmonary epithelial cells and macrophages, supporting a picture of tissue-specific iron dysregulation and enhanced ferroptotic vulnerability." (PMID 41516398, 2026). "Furthermore, host receptors documented in COVID-19 individuals include dipeptidyl peptidase-4 (DPP4), transferrin receptor (TFRC), and extracellular high mobility group box 1 (HMBG1)." (PMID 41488148, 2025). "However, compared to HD, the frequency of monocytes expressing the transferrin receptor (CD71), an indirect activation marker, was increased in COVID-19 individuals without stimulation (p<0.05), in response to spike (p<0.01) and to BCG (p<0.05)." (PMID 40458413, 2025).
colorectal cancer (32 papers, 2013 to 2025). A primary or metastatic malignant neoplasm that affects the colon or rectum. "Transferrin Receptor 1 (TfR1/CD71) is frequently overexpressedin colorectal cancer (CRC) and is associated with poor clinical outcomes,making it a compelling target for molecular imaging." (PMID 41476540, 2025). "Here the work shows TFRC is induced by adenomatous polyposis coli (APC) gene loss‐driven β‐catenin activation in colorectal cancer, whereas TFRC‐mediated intratumoral iron accumulation potentiates β‐catenin signaling by directly enhancing the activity of tankyrase." (PMID 36703617, 2023). "For instance, studies have shown that TFRC expression is significantly elevated in various cancer types, including breast, gastric, and colorectal cancers, where it correlates with poor prognosis and aggressive tumor behavior." (PMID 40303995, 2025). "In colorectal cancer, CD71/TFRC-mediated iron uptake sustains β-catenin/tankyrase activity and tumorigenesis, a pathway intimately tied to EMT and invasion programs." (PMID 41375568, 2025). "Insulin-like growth factor 2 mRNA-binding protein 2 (IGF2BP2) can preserve the stability of TFRC mRNA through m6A modifications, thereby increasing TFRC protein levels in colorectal cancer (CRC) cells and facilitating the growth of CRC." (PMID 38602575, 2024). "Previous works have evidenced that TFRC expression seems to follow a 24-h rhythm in mRNA and protein levels in colorectal cancer cells, particularly through the oncogene c-myc." (PMID 39199335, 2024). "Our results indicate that knockdown of ANAX10 can inhibit the malignant capacity of colorectal cancer cells by inhibiting autophagy-mediated degradation of TFRC, leading to cellular ferroptosis." (PMID 37666806, 2023). "TFRC has been suggested as a potential biomarker in the diagnosis of early onset of colorectal cancer." (PMID 25419056, 2014). "In HT-29 colorectal cell lines, EGCG upregulated the activity of TfR (Transferrin receptor), which is a carrier protein for transferrin, and inhibited the activity of the Ferritin-H protein via the iron chelation activity in HT-29 colorectal cancer cells." (PMID 32717865, 2020). "Additionally, grape-derived exosome-like nanovesicles can deliver natural polyphenols, downregulate GPX4, upregulate transferrin receptor 1 (TFR1), and enhance iron uptake, leading to excessive ROS accumulation and ferroptosis, effectively inhibiting colorectal cancer cell proliferation." (PMID 40642010, 2025). "YAP promotes ferroptosis in colorectal cancer by transcriptionally upregulating acyl-CoA synthetase long-chain family member 4 (ACSL4) and transferrin receptor (TFRC) expression." (PMID 40619484, 2025). "From the literature we know that CEA is increased in tumor tissue, that the MIF (Hs.407995) is up-regulated in colorectal carcinomas, that OPN is significantly higher in CRC tumor tissue compared to normal tissue and that TFRC is higher in tumor tissue compared to normal mucosa." (PMID 24107468, 2013).
liver cancer (31 papers, 2016 to 2025). An epithelial or non-epithelial malignant neoplasm that arises from the liver. "Since gene expression does not always correlate with the level of a protein encoded by the corresponding gene, the level of TFRC was measured in liver cancer cells." (PMID 26657500, 2016). "Yes1-associated transcriptional regulator (YAP) O-GlcNAcylation facilitates transferrin receptor transcription and induces ferroptosis by increasing iron concentration in liver cancer cells." (PMID 40740652, 2025). "The transferrin receptor (TfR) is crucial in cellular iron uptake, overexpressed on liver cancer cells’ surface, making it a potential target for drug delivery." (PMID 38990300, 2024). "Here, we showed that the transferrin receptor CD71 was upregulated on activated Tregs infiltrating human liver cancer." (PMID 38954474, 2024). "Overall, we found for the first time that LASS2 directly interacts with TFRC in thyroid, breast, and liver cancer cell lines." (PMID 38419028, 2024). "TFRC was modified by O-GlcNAcylation, affecting its sensitivity to erastin-induced ferroptosis in liver cancer cells." (PMID 39199296, 2024). "TRIB2 regulated the β-TrCP-induced ubiquitination of TFRC, resulting in ferroptosis desensitization in liver cancer cells." (PMID 39199296, 2024). "More importantly, in the present study, the single-cell sequencing analysis results implied that SLC7A11, SLC1A5, CARS1, RPL8 and TFRC were not only upregulated in liver cancer cells but also expressed in immune cells." (PMID 35847985, 2022). "It seems that the remaining low level of Ub in liver cancer cells is sufficient for βTrCP to ubiquitinate TFRC." (PMID 34315867, 2021). "The effects by which βTrCP-mediated ubiquitination and followed degradation of TFRC to decline labile iron are critical for TRIB2 to desensitize liver cancer cells to ferroptosis." (PMID 34315867, 2021). "DOX@Fe-HMON-Tf NPs had surface-modified transferrin, and transferrin receptor-overexpressing liver cancer cells had a high affinity for them." (PMID 34749740, 2021). "In conclusion, we elucidated a novel role of TRIB2 to desensitize ferroptosis via E3 βTrCP, by which facilitates TFRC ubiquitiation and finally decreases labile iron in liver cancer cells." (PMID 34315867, 2021). "In light of this, the role of epigenetic mechanisms in TFRC dysregulation at the transcriptional level in human liver cancer cells was investigated." (PMID 26657500, 2016). "We found substantial up-regulation of TFRC in preneoplastic livers, human liver cancer cell lines, and human HCC tissue samples." (PMID 26657500, 2016). "In the present study, we investigated the role and mechanisms of TFRC dysregulation in liver carcinogenesis by using two rat models of hepatocarcinogenesis, human liver cancer cell lines, and human HCC gene expression data." (PMID 26657500, 2016). "The silencing of TFRC gene reduces liver cancer cell growth and survival." (PMID 34906147, 2021). "Together, βTrCP is required for TRIB2 to modulate the ubiquitination of TFRC in liver cancer cells." (PMID 34315867, 2021). "As knocking out TFRC and βTrCP plays contrary roles to control labile iron, and tumor cells often show iron addiction to sustain cell proliferation; we were curious to know whether TFRC and βTrCP are also essential for cell proliferation in liver cancer cells." (PMID 34315867, 2021). "One study showed that TFRC and FTH1 were silenced by estrogen in liver cancer, leading to reductions in cell growth and survival." (PMID 39199296, 2024). "Then, we assessed whether TFRC and βTrCP contribute to the effects by which TRIB2 desensitizes liver cancer cells to ferroptosis that induced by RSL3 and erastin." (PMID 34315867, 2021).
liver cancer (continued). "For example, biological targets identified in human liver cancer cells using a library of tagged C75 analogs revealed previously unknown putative C75 targets, including protein disulfide-isomerase A3 (PDIA3), transferrin receptor (TRFC), and glyceraldehyde-3-phosphate dehydrogenase (GAPDH)." (PMID 31681794, 2019).